KLF5 (KLF transcription factor 5)
Diseases named in the same sentence as KLF5 in open-access papers (continued):
Sharing a sentence is not in itself a finding about the gene and the disease.
lung carcinoma (continued). "The highly expressed oncogenic factor Krüppel‐like factor 5 (KLF5) promotes various cancerous processes, such as cell growth, survival, anti‐apoptosis, migration and metastasis, particularly in lung cancer." (PMID 37461162, 2023). "Despite its potential as a therapeutic target, the function of KLF5 in cancer is complex and context‐dependent, especially in lung cancer." (PMID 37461162, 2023). "Further investigation showed that PRMT5 directly interacted with and methylated KLF5 in human lung cancer cells." (PMID 37461162, 2023). "To confirm our findings, we assessed the mRNA and protein expression levels of PRMT5 and KLF5 in lung cancer cell lines and normal human foetal lung fibroblast cells (IMR90)." (PMID 37461162, 2023). "In summary, PRMT5 methylates KLF5 to prevent its degradation, thereby promoting the maintenance and proliferation of lung cancer cells." (PMID 37461162, 2023). "KLF5 mRNA expression was significantly higher in lung cancer tissues compared to the matched normal tissues." (PMID 37461162, 2023). "While KLF5 has been identified as a potential therapeutic target in lung cancer, further research is needed to fully understand its function and potential as a treatment target in this disease." (PMID 37461162, 2023). "Collectively, our findings suggest that PRMT5 methylates KLF5 at arginine 41 to stabilize KLF5 and promote lung cancer cell growth." (PMID 37461162, 2023). "Altogether, our findings indicate that PRMT5 directly interacts with and methylates KLF5 in human lung cancer cells." (PMID 37461162, 2023). "In our study, we demonstrated that KLF5 was overexpressed in lung cancer and significantly correlated with patients' survival rate." (PMID 37461162, 2023). "Single cell sequencing analysis also demonstrated that a subset of lung cancer cells with high KLF5 expression has a concomitant elevation of MLK4." (PMID 37407566, 2023). "Collectively, KLF5 promotes lung cancer cell proliferation and migration and promotes STK24 expression." (PMID 37181807, 2023). "GCN5 forms a complex with KLF5 and promotes KLF5 acetylation to facilitate lung cancer cell proliferation." (PMID 35342356, 2022). "The prognostic significance of KLF5 upregulation seen in our cohort is similar to previously reported studies in other organ sites, like pancreatic, gastric and lung cancers." (PMID 33430300, 2021). "More importantly, a previous study revealed that KLF5 transcriptionally repressed the expression of ATP-binding cassette subfamily G member 2 (ABCG2) and KLF5 knockdown increased the resistance of lung cancer cells to doxorubicin treatment." (PMID 29898734, 2018). "Emerging evidence has also identified KLF5 as an oncoprotein in various human malignancies, such as esophageal squamous carcinoma, colorectal cancer, prostate cancer, esophageal adenocarcinoma, and lung cancer." (PMID 39827156, 2025). "Studies have shown that KLF5 is overexpressed in lung cancer and may contribute to its development and progression." (PMID 37461162, 2023). "Enhanced lung cancer cell growth and migration triggered by KLF5 could be reversed by silencing of STK24." (PMID 37181807, 2023). "In particular, KLF5 has been shown to promote cell proliferation and invasion in lung cancer cells." (PMID 37461162, 2023). "Treatment with GSK591 also blocked the methylation of KLF5 by PRMT5 in lung cancer cells." (PMID 37461162, 2023). "Targeting PRMT5/KLF5 and its downstream signalling pathways may represent a promising therapeutic strategy for lung cancer treatment." (PMID 37461162, 2023). "Here, we show that the expression levels of PRMT5 and KLF5 are highly expressed lung cancer." (PMID 37461162, 2023). "Based on these findings, we proposed that targeting STK24 might be a potential therapy for lung cancer patients with highly expressed KLF5." (PMID 37181807, 2023). "In conclusion, KLF5 upregulation of STK24 promotes lung cancer growth and migration." (PMID 37181807, 2023).
lung carcinoma (continued). "Interestingly, when KLF5 overexpression promoted lung cancer cell proliferation and migration, the knockdown of STK24 significantly blocked the oncogenic role of KLF5." (PMID 37181807, 2023). "Collectively, our study highlights KLF5 as a new target for PRMT5 to promote lung cancer." (PMID 37461162, 2023). "Moreover, GEPIA website also found a positive correlation between BBOX1-AS1 and KLF5 in lung cancer tissues." (PMID 33931086, 2021). "In colon and lung cancer cells, KLF5 was shown to directly regulate the transcription of HIF1α." (PMID 25896712, 2015). "Furthermore, Krüppel-like factor 5 (KLF5) activated STK24 in lung cancer cells and tissues." (PMID 37181807, 2023). "We investigated whether GSK591, a specific inhibitor of PRMT5, could control KLF5 expression and proliferation in lung cancer cells, as PRMT5 has emerged as a promising therapeutic target for cancer treatment, and several specific small‐molecule inhibitors of PRMT5 have been developed." (PMID 37461162, 2023). "Therefore, KLF5 upregulation of STK24 may contribute to the progression of lung cancer in both cells and patients." (PMID 37181807, 2023). "KLF5 and hypoxia-inducible factors 1α (HIF-1α) in the micro-environment of lung cancer are correlated, because hypoxia can increase the activity, clonality and proliferation of A549 cells, and inhibit cell apoptosis." (PMID 38560274, 2024). "To explore the expression and potential function of KLF5 and PRMT5 in lung cancer, we first evaluated the mRNA expression of KLF5 in lung cancer tissues and matched normal tissues." (PMID 37461162, 2023). "Mechanistically, the dimethylation of KLF5 by PRMT5 promotes the maintenance and proliferation of lung cancer cells at least partially by stabilising KLF5 via regulation of the Akt/GSK3β signalling axis." (PMID 37461162, 2023). "The network analysis in LUSC identified key TFs including KLF5 and MYC in basal cells, consistent with its amplification and overexpression in lung cancer patients, acting as the prognostic markers of early-stage tumors." (PMID 35027529, 2022). "First, functional studies show KLF5 co-immunoprecipitates with HIF-1α, which is consistent with previous studies in lung cancer cells." (PMID 33430300, 2021). "To discover whether PRMT5 interacts with KLF5 in human lung cancer cells, we used the immunoprecipitation (IP) method to detect the endogenous interaction between PRMT5 and KLF5." (PMID 37461162, 2023). "Importantly, PRMT5‐mediated KLF5 stabilisation induced the expression of target genes such as cyclin D1, slug and FGF‐BP1, which facilitated lung cancer cell proliferation and EMT." (PMID 37461162, 2023). "Of these genes, human homologs of 4 genes including Inhibin, beta A (INHBA), Kruppel-like factor 5 (KLF5), Serine/threonine/tyrosine kinase 1 (STYK1), and stem cell marker ALDH1A1 are previously shown to be over-expressed in NSCLC and involved in lung cancer progression and tumorigenicity." (PMID 28415606, 2017).
cardiac hypertrophy (21 papers, 2011 to 2026). "This indicates that the knockout of KLF5 can minimize the cardiac hypertrophy and fibrosis caused by Ang II infusion." (PMID 35457114, 2022). "KLF5 is also expressed in myocardial myofibroblasts, and Ang II loading causes considerably less cardiac fibrosis and hypertrophy in KLF5+/− mice." (PMID 35457114, 2022). "In addition to GATA, MEF2 and NFAT families, other transcription factors, such as UBF1 86, ATF3 87, T-Cdk9 88, XBP1 89, MITF 90, HSF1 91, C/EBP 92, KLF11 93 and KLF5/BTEB2 94 have been implicated in regulating cardiac hypertrophy." (PMID 39239522, 2024). "KLF5 is essential in cardiovascular remodeling, acting as a transcriptional regulator that promotes cardiac hypertrophy and fibrosis under stress conditions such as pressure overload." (PMID 41526530, 2026). "NC114, a novel peptidomimetic molecule, targets the undruggable transcription factor KLF5 to attenuate cardiac hypertrophy, fibrosis, and metabolic dysregulation in pressure overload-induced heart failure." (PMID 41526530, 2026). "Heterozygous KLF5-knockout mice showed decreased cardiac remodeling after induced vascular injury, and in a similar way, H2S has been found to decrease myocardial hypertrophy through mechanisms of downregulating KLF5 gene expression." (PMID 39156383, 2024). "KLF5 is responsible for orchestrating cardiovascular remodeling through cardiac hypertrophy, fibrosis, arterial wall thickening, and angiogenesis." (PMID 39156383, 2024). "H2S reduces the promoter activity of Krüppel-like factor 5 (KLF5) and the expression of mRNA, and the S-sulfhydration of SP-1 by H2S at Cys664 weaken the activity of SP-1 and KLF5 promoter binding and inhibits cardiac hypertrophy." (PMID 37492730, 2023). "Krüppel-like zinc-finger transcription factor 5 (KLF5), also known as BTEB2 and IKLF, played a crucial role in the progression of cardiac hypertrophy caused by angiotensin II." (PMID 38074127, 2023). "KLF5 deletion in cardiac fibroblasts has improved cardiac hypertrophy and fibrosis, demonstrating that KLF5 in fibroblasts is crucial for pressure-overload response." (PMID 35457114, 2022). "Due to the lower expression of TGF-β in hearts of Klf5+/− mice, it can also protect KLF5+/− mice from cardiac hypertrophy and fibrosis." (PMID 35457114, 2022). "Despite the fact that KLF5 is vital in pressure overload-induced cardiac hypertrophy, the specific involvement of KLF5 in cardiac hypertrophy and heart failure is still unclear." (PMID 35457114, 2022). "KLF5 haploinsufficiency prevents moderate-intensity pressure overload-induced cardiac fibrosis and hypertrophy." (PMID 35457114, 2022). "In recent years, KLF5 is found to be significant in the progression of AS and cardiac hypertrophy, as well as cell growth of cardiomyocytes and smooth muscle cells." (PMID 34925646, 2021). "Pressure overload upregulates KLF5, which promotes cardiac hypertrophy and proliferates cardiac fibroblasts." (PMID 34290289, 2021). "The Nagai group recently reported that the global heterozygous knockout of Klf5 reduced cardiac hypertrophy and fibrosis induced by Ang II infusion." (PMID 32435205, 2020). "Ang II infusion in heterozygous KLF5 knockout mice resulted in reduced cardiac hypertrophy and interstitial fibrosis compared with wild type mice." (PMID 29970016, 2018). "The KLF5 was an important signaling contributed to the development of cardiac hypertrophy induced by angiotensin II." (PMID 28932194, 2017). "In addition, Pterosin B derived from natural products can not only inhibit KLF5 expression, but also improve cognitive impairment and alleviate myocardial hypertrophy simultaneously, demonstrating multi-target therapeutic potential." (PMID 41583492, 2025). "We propose that ICG001 may control pathological cardiac hypertrophy and fibrosis via KLF5, immune activation, and the Wnt/β-catenin signaling pathway by connecting with TGF-β as a mediator." (PMID 34290289, 2021).
cardiac hypertrophy (continued). "We next investigated whether ICG001 is associated with the roles of KLF5 and PPAR-α in responding cardiac hypertrophy and fibrosis." (PMID 34290289, 2021). "Moreover, KLF5 promotes cardiac hypertrophy and regulates peroxisome proliferator-activated receptor alpha (PPAR-α) expression." (PMID 34290289, 2021). "In conclusion, ICG001 is a potential drug that may prevent cardiac hypertrophy and fibrosis by regulating KLF5, immune activation, and the Wnt/β-catenin signaling pathway and inhibiting the inflammatory response involving macrophages." (PMID 34290289, 2021). "It is reported that KLF5 is involved in the development of myocardial hypertrophy and fibrosis, and it could affect the pathological level of myocardial injury through activating the downstream pathways." (PMID 34925646, 2021). "In conclusion, ICG001 is a potential drug that may prevent cardiac hypertrophy and fibrosis through regulating KLF5, immune activation, and the Wnt/β-catenin signaling pathway and also inhibiting the inflammatory response involving the macrophages." (PMID 34290289, 2021). "Thus, ICG001 inhibits cardiac β-catenin activation in Wnt/β-catenin signaling and might have an impact on protective effects against cardiac hypertrophy and fibrosis via KLF5 and PPAR-α." (PMID 34290289, 2021). "Thus, ICG001 may have protective effects against cardiac hypertrophy and fibrosis via the regulation of KLF5, immune activation, and the Wnt/β-catenin signaling pathway and may also inhibit the inflammatory response involving macrophages." (PMID 34290289, 2021). "By targeting KLF5, NC114 effectively reduces cardiac hypertrophy, fibrosis, inflammation, and oxidative stress while restoring metabolic balance." (PMID 41526530, 2026). "In this case, the modification of Cys664 abolished the Krüppel-like factor 5 (KLF5) promoter binding to SP-1 and inhibited cardiac hypertrophy (because when SP-1 is coupled with KLF5 promoter, it has a pro-hypertrophic effect in the heart)." (PMID 38247849, 2024). "Consequently, the expression of KLF5 and MMP2 is downregulated, leading to the suppression of cardiac hypertrophy and the attenuation of pathological changes in aortic aneurysms, respectively." (PMID 39252788, 2024). "Because KLF5 induces ECM reorganization and can activate the promoter of PAI-1, which is an inhibitor of fibrin degradation, it contributes to accumulating ECM and leads to vascular wall thickening and cardiac hypertrophy." (PMID 35457114, 2022). "KLF5 activates the promoter of PAI-1, an inhibitor of fibrin degradation, thus contributing to ECM accumulation and leading to vascular wall thickening and cardiac hypertrophy." (PMID 33493334, 2021). "Of these only KLF4, KLF5, KLF10, KLF11 and KLF15 have been studied in cardiac hypertrophy." (PMID 29970016, 2018).
ovarian carcinoma (21 papers, 2006 to 2025). A malignant neoplasm originating from the surface ovarian epithelium. "High-throughput sequencing was conducted on SKOV3-sh-KLF5 and control cell lines to investigate downstream regulatory mechanisms associated with KLF5-induced ovarian cancer resistance to PARPi." (PMID 40307891, 2025). "Relevantly, expression of MIR196A1 miRNA has been correlated with expression of the endometrial cancer candidate target gene KLF5 in breast tumors, and has been associated with poor outcome in breast and ovarian cancer patients." (PMID 31561579, 2019). "These precedents suggest that the upregulation of IL-8 and KLF5 observed in ZO-1-deficient ovarian cancer cells may reflect a broader function of ZO-1 in modulating transcriptional activity, linking tight junction integrity to gene expression pathways that drive angiogenesis." (PMID 40943311, 2025). "To investigate the role of Vimentin in the promotion of stemness and PARPi resistance in ovarian cancer by KLF5, we conducted Vimentin rescue experiments." (PMID 40307891, 2025). "By comparing RNA-Seq data from PARPi-sensitive and resistant cell lines and conducting a series of experiments, we found that KLF5 is highly expressed in PARPi-resistant ovarian cancer cell lines." (PMID 40307891, 2025). "KLF5 enhances stemness and contributes to PARPi resistance in ovarian cancer through Vimentin regulation." (PMID 40307891, 2025). "In summary, this study validates that KLF5 increases ovarian cancer cell stemness and induces PARPi resistance by binding to Vimentin and regulating its expression." (PMID 40307891, 2025). "In this study, we focus on exploring how KLF5 modulates ovarian cancer stem cell properties to induce PARPi resistance." (PMID 40307891, 2025). "In conclusion, our findings reveal that ZO-1 suppresses angiogenesis in ovarian cancer by negatively regulating pro-angiogenic mediators such as IL-8 and KLF5." (PMID 40943311, 2025). "Collectively, these results suggest that IL-8 and KLF5 are key mediators of ZO-1–regulated angiogenesis in ovarian cancer cells." (PMID 40943311, 2025). "In this study, we confirmed the regulatory role of KLF5 in ovarian cancer cell stemness, focusing on the mechanisms by which this process contributes to PARPi resistance in ovarian cancer." (PMID 40307891, 2025). "Following KLF5 silencing using small interference RNA, the sphere forming assay revealed a decrease in both the volume and quantity of ovarian cancer cells." (PMID 40307891, 2025). "Our findings suggested that KLF5 played a role in regulating PARPi resistance and stemness of ovarian cancer through the modulation of Vimentin expression." (PMID 40307891, 2025). "Specifically, highly expressed in ovarian cancer, KLF5 facilitated the process of ovarian cancer proliferation and metastasis and promoted PARP inhibitor resistance by remodeling the transcription of the key gene for homologous recombination, RAD51." (PMID 38773440, 2024). "Another combination approach targets a transcription factor, KLF5 (Kruppel-like factor 5), which promotes ovarian cancer growth and metastasis." (PMID 39201718, 2024). "It is worth noting that we have identified that KLF5 is regulated by super‐enhancers and self‐regulation in OC, resulting in the formation of two subgroups: the super‐enhancer‐driven KLF5 ovarian cancer subgroup and the self‐regulatory KLF5 subgroup." (PMID 37702443, 2023). "Immunofluorescence staining revealed that inhibition of KLF5 reduced RAD51 foci and increased γ‐H2AX foci, suggesting that KLF5 plays a crucial role in regulating HRR in ovarian cancer cells." (PMID 37702443, 2023). "This study depicts the landscape of abnormally activated super‐enhancer regulatory elements in ovarian cancer (OC) and identifies two super‐enhancers that regulate Kruppel‐like factor 5 (KLF5) transcription, resulting in KLF5 self‐transcriptional regulation." (PMID 37702443, 2023).